CCDC80 (coiled-coil domain containing 80)
Diseases named in the same sentence as CCDC80 in open-access papers (continued):
Sharing a sentence is not in itself a finding about the gene and the disease.
Hypertension (3 papers, 2018 to 2025). The presence of chronic increased pressure in the systemic arterial system. "Based on the findings of this study and the functions of their encoded products, two genes (FHIT and CCDC80) are potentially relevant to IA with strong aggregation of familial IA cases with high blood pressure in the French-Canadian population." (PMID 29531279, 2018).
pulmonary arterial hypertension (3 papers, 2016 to 2024). Pulmonary arterial hypertension (PAH) is a group of diseases characterized by mean pulmonary artery pressure >20 mmHg and elevated pulmonary arterial resistance leading to right heart failure. "Coiled‐coil domain‐containing protein 80 (CCDC80), located in the extracellular matrix and characterized by its glycosaminoglycan‐binding activity, has emerged as a potential biomarker and therapeutic target for pulmonary arterial hypertension (PAH)." (PMID 39725655, 2024).
breast carcinoma (2 papers, 2022 to 2025). "In mammary carcinoma cells carrying an oncogenic activation of AIB1, inhibition of apoptosis has been shown to be at least partly mediated by repression of DRO1/CCDC80 expression." (PMID 35422964, 2022).
colon adenocarcinoma (2 papers, 2022 to 2024). "Loss of DRO1/CCDC80 increases multiplicity of preneoplastic aberrant crypt foci and colonic tumors in carcinogen-induced colon carcinogenesis and promotes formation of colon adenocarcinoma during inflammation-driven carcinogenesis." (PMID 35422964, 2022).
fibrosis (2 papers, 2023 to 2025). the formation of excess fibrous connective tissue in an organ or tissue in a reparative or reactive process. "CCDC80, LAMA4, PDGFRB, PODN, and SPARC are potential mediators of intestinal fibrosis due to common expression among ileal and colonic strictures." (PMID 40398622, 2025). "We observed significantly increased differential expression of CCDC80 in individuals with NAFLD, using 3 independent tests comparing individuals with steatosis, fibrosis, and NASH to those with healthy livers." (PMID 37224770, 2023). "Because CCDC80 and SOD3 were observed as the strongest SBCs for both fibrosis and NASH, we next investigated their effects on adipogenesis in vitro using an siRNA knockdown experiment." (PMID 37224770, 2023).
lung carcinoma (2 papers, 2021 to 2024). "In addition, the suppressing role of CCDC80 in EMT processes should be examined in other carcinoma types than pancreatic, hepatocellular, and lung carcinoma." (PMID 33928036, 2021).
papillary thyroid carcinoma (2 papers, 2020 to 2024). "However, contrary to our observation, CXCR4 is observed to highly expressed in high-grade serous epithelial OC which positively related to tumor dissemination and metastasis while CCDC80 is down-regulated in papillary thyroid carcinomas and considered as a tumor suppressor role." (PMID 32716025, 2020). "Furthermore, in papillary thyroid carcinoma, a group of iCAFs with a remarkable expression of CFD, DCN, or CCDC80, facilitated the migration of tumor cells through ECM degradation." (PMID 39003267, 2024).
Atopic dermatitis (1 paper, 2024). "Atopic dermatitis whole genome association study and downstream analysis suggest that the expression signals of CCDC80 overlap significantly in enhancers of skin cells and immune cells, particularly CD4 T cells." (PMID 38872096, 2024).
bladder cancer (1 paper, 2023). "At present, it has been found that the increased expression of CCDC80 can enhance the sensitivity of tumor cells to chemotherapy drugs, and knocking it down in cancer cells can enhance the anti-cancer drug resistance effect of bladder cancer cells." (PMID 37275895, 2023).
cardiac hypertrophy (1 paper, 2025). "Exercise stimulation induced cardiac-specific expression of the C-terminal domain of CCDC80, which prevented angiotensin II-induced cardiac hypertrophy and fibrosis in mice." (PMID 41158506, 2025).
colon tumors (1 paper, 2022). "In colon tumors from ApcMin/+ mice loss of DRO1/CCDC80 induces ERK1/2 phosphorylation and leads to c-MYC oncogene activation." (PMID 35422964, 2022). "Similarly, despite Dro1/Ccdc80’s strong tumor suppressive function in ApcMin/+ mice as well as chemically-induced colon carcinogenesis, ubiquitous loss of DRO1/CCDC80 alone was insufficient to induce spontaneous colonic tumor development in C57BL/6 mice." (PMID 35422964, 2022). "To further investigate the role of epithelial Dro1/Ccdc80 in colon tumorigenesis, specifically in stemness, we established epithelial organoid cultures from colon tumors that were harvested from Dro1−/−;ApcMin/+ and ApcMin/+ control mice." (PMID 35422964, 2022). "Consistently, Dro1/Ccdc80 expression was strongly reduced in PSC isolated from colon tumors from moribund ApcMin/+ mice compared to PSC generated from tumor-free colon from 5-week-old ApcMin/+ mice." (PMID 35422964, 2022). "Ubiquitous inactivation of Dro1/Ccdc80 in ApcMin/+ mice results in early death, a dramatic increase in colon tumor number, and formation of adenocarcinoma in the colon." (PMID 35422964, 2022). "Previously we have shown activation of both pERK1/2 and oncogenic c-MYC in colon tumors from ApcMin/+ mice upon ubiquitous inactivation of Dro1/Ccdc80." (PMID 35422964, 2022). "In ApcMin/+ mice ubiquitous inactivation of Dro1/Ccdc80 results in early death, a significant increase in the colonic tumor load, and the regular formation of adenocarcinoma in the colon." (PMID 35422964, 2022). "Consistently, we demonstrated ubiquitous inactivation of Dro1/Ccdc80 to implicate increased c-MYC protein levels in the colonic epithelium and in colon tumors from ApcMin/+ mice." (PMID 35422964, 2022). "Ubiquitous inactivation of Dro1/Ccdc80 leads to increased phosphorylation of ERK1/2 and oncogenic c-MYC activation in colon tumors from ApcMin/+ mice." (PMID 35422964, 2022). "Colon tumor development in ApcMin/+ mice as well as formation of xenograft tumors was unaffected by Dro1/Ccdc80 expression in cancer cells, suggesting epithelial derived DRO1/CCDC80 to be dispensable for intestinal tissue homeostasis." (PMID 35422964, 2022). "Dro1/Ccdc80 inactivation did not improve growth of epithelial organoids derived from ApcMin/+ colon tumors, providing further evidence that the tumor suppressive function of DRO1/CCDC80 is not tumor-cell-autonomous but dictated by extrinsic cues provided by the local tissue microenvironment." (PMID 35422964, 2022).
esophageal cancer (1 paper, 2024). A primary or metastatic malignant neoplasm involving the esophagus. "CCDC80 is characterized by promoter hypomethylation and upregulation in esophageal cancer." (PMID 38872096, 2024).
hip fracture (1 paper, 2025). Traumatic or pathological injury to the hip in which the continuity of either the femoral head, femoral neck, intertrochanteric or subtrochanteric regions is broken. "In the first observational part of our study, increasing concentrations of the adipocytokine coiled-coil domain-containing 80 (CCDC80) were related to higher hip fracture risk, lower BMD and bone area, higher bone turnover, lower lean mass, and higher fat mass." (PMID 39919333, 2025).
joint disease (1 paper, 2024). "Our study indicates that CCDC80 may prove to be a useful diagnostic marker for OA that could directly link the thyroid hormone pathway and joint disease." (PMID 38664820, 2024).
ovarian tumors (1 paper, 2021). "Regarding DO enrichment, CCDC80-related downregulated DEGs may participate in some pulmonary and cardiovascular diseases, while CCDC80-related upregulated DEGs may participate in ovarian tumors and urinary system cancer." (PMID 34820451, 2021).
stricture (1 paper, 2025). "Coiled-coil domain-containing 80 (CCDC80) and laminin subunit alpha 4 (LAMA4) are common among pediatric ileal and adult colonic strictures." (PMID 40398622, 2025).
Thyroid adenoma (1 paper, 2020). The presence of a adenoma of the thyroid gland. "Treating with CXCR4 antagonists significantly inhibits tumor pro-invasive phenotype and knockdown of CCDC80 is susceptible to developed thyroid adenoma and OC." (PMID 32716025, 2020).
thyroiditis (1 paper, 2022). Inflammation of the thyroid gland. "Samples from PTC patients without thyroiditis showed high expression of TFF3 while PTC with thyroiditis high expression of CCDC80." (PMID 36077831, 2022).
tumor (34 papers, 2010 to 2026). "CCDC80 likely mediates diacylglycerol (16:1_18:1)-linked GC progression through coordinated regulation of signaling pathways, epigenetic modifications, and tumor microenvironment remodeling, positioning it as a central hub in lipid-driven oncogenesis." (PMID 40388730, 2025). "The data from the present study suggest microenvironmental loss of Dro1/Ccdc80’s tumor suppressive function to be an important event during carcinogenesis." (PMID 35422964, 2022). "Future studies are needed to further elucidate the molecular mechanisms underlying Dro1/Ccdc80’s microenvironmental tumor suppressive function and to better characterize its role in human cancer." (PMID 35422964, 2022). "For the study of tumorigenesis this approach implicates Dro1/Ccdc80 deficiency in both the tumor parenchyma and the tumor microenvironment." (PMID 35422964, 2022). "In contrast, DRO1/CCDC80 loss in the microenvironment strongly increased tumor growth in xenograft models, inhibited cancer cell apoptosis, and promoted intestinal epithelial cell migration." (PMID 35422964, 2022). "Loss of CCDC80 increased the development of carcinoma in ApcMin/− mice, suggesting that CCDC80 acts as a tumor suppressor in colon tumorigenesis." (PMID 34746152, 2021). "Thus, loss of Dro1/Ccdc80 function in the tumor stroma might promote cancer progression by creating a permissive environment for cancer cell migration." (PMID 35422964, 2022). "Our findings indicate that PAX8 negatively regulates CCDC80, a novel cell autonomous tumor suppressor in HGSC." (PMID 42011738, 2026). "To date, most research on CCDC80 has focused on its expression and functional characteristics in tumor cells." (PMID 40534859, 2025). "Our study demonstrates that reduced CCDC80 expression mediates the tumor-promoting effects of diacylglycerol (16:1_18:1) in GC pathogenesis." (PMID 40388730, 2025). "The examination of tumor tissue showed that CCDC80 and PCNA proteins expression in si-CCDC80 group was lower than si-NC group." (PMID 38872096, 2024). "The results also preliminarily confirmed the inhibitory effect of si-CCDC80 on tumor formation (3 nude mice per group)." (PMID 38872096, 2024). "In humans, CCDC80 is expressed in various tumor cell lines and tissues, and is a potential oncogenic factor." (PMID 38872096, 2024). "We utilized flow cytometry to analyze the polarization of macrophages in tumor tissues and found that silencing CCDC80 promoted M1 polarization while inhibited M2 polarization." (PMID 38872096, 2024). "CCDC80 staining was significantly more intense in GC tissue specimens (score ≥4, 73.8% [59/80]) than in adjacent non-tumor tissue specimens (score ≥4, 47.5% [38/80]) (p = 0.001)." (PMID 39308689, 2024). "Consistent with our observations in ApcMin/+ mice, growth and histology of xenograft tumors were unaffected by Dro1/Ccdc80 expression in tumor cells." (PMID 35422964, 2022). "DRO1/CCDC80 in the stromal compartment strongly inhibited tumor growth, facilitated apoptosis in cancer cells, and reduced epithelial cell migration." (PMID 35422964, 2022). "In contrast, mutational inactivation of host Dro1/Ccdc80 highly promotes growth of xenograft tumors, suggesting a strong tumor suppressive role for microenvironmental Dro1/Ccdc80." (PMID 35422964, 2022). "Adhesion of chick lens cells and various tumor cell lines has been demonstrated to be mediated by DRO1/CCDC80 through heparin sulfate proteoglycan." (PMID 35422964, 2022). "Our results demonstrate epithelial derived DRO1/CCDC80 to be dispensable for intestinal tissue homeostasis and identify Dro1/Ccdc80 as tumor suppressor in the tumor microenvironment." (PMID 35422964, 2022). "After TCGA analysis for the differentially expressed genes, we found that the expression of CCDC80, a gene downregulated by NP treatment, was significantly lower in tumor tissues than in normal tissues." (PMID 34746152, 2021).
tumor (continued). "The results showed that NP treatment significantly increased tumor growth, and that the overexpression of CCDC80 significantly suppressed tumor growth, even when co-treated with NP." (PMID 34746152, 2021). "The CL2/DRO1/CCDC80 served as tumor suppressor genes in thyroid carcinogenesis 26 The rho‐specific guanine nucleotide exchange factor DBS (MCF2L) can regulate breast cancer cell migration." (PMID 32783399, 2020). "Particularly, the expression of tumour-suppressing gene Ccdc80 was induced by vactosertib and further induced by vactosertib in combination with nal-IRI/5-FU/LV." (PMID 32076068, 2020). "In regard to cancer, mRNA expression of CCDC80 is often down-regulated in various cancer cell lines and tumour tissues, suggesting the tumour-suppressive role of CCDC8024,43,46,47." (PMID 32076068, 2020). "From RNA-Seq analysis, we found that tumour suppressors such as Ccdc80, Itm2a, and Sfrp1 were significantly up-regulated by the combination treatment of vactosertib with nal-IRI/5-FU/LV compared to the control group and the nal-IRI/5-FU/LV group." (PMID 32076068, 2020). "Rat, mouse and human CCDC80 show three P-DUDES domains (Procaryotes- DRO1-URB-DRS-Equarin-SRPUL) which in human are correlated with a tumor suppressor role." (PMID 22384085, 2012). "Here, we start with three human proteins, SRPX, SRPX2 and CCDC80, involved in tumor suppression and progression, which possess a conserved region of similarity." (PMID 20964819, 2010). "Overall, these results suggest that CD8+ cytotoxic T cells with high CCDC80 expression exhibit inhibited cytotoxicity activities against tumor cells, which may contribute to immune evasion and promote an immunosuppressive TIME." (PMID 40534859, 2025). "Silencing CCDC80 inhibited M2 polarization and promoted M1 polarization in tumor tissues." (PMID 38872096, 2024). "Finally, immunohistochemical staining was used to evaluate CCDC80 expression in normal and tumor tissues." (PMID 39308689, 2024). "Both GC and adjacent non-tumor tissue specimens exhibited cytoplasmic CCDC80 expression." (PMID 39308689, 2024). "Elevated levels of crucial genes such as INHBB, CCDC80, and S100A11 could be significantly linked to tumor development, progression, and the modulation of the tumor microenvironment." (PMID 39850875, 2024). "Because of its structural domains, CCDC80 gained considerable interest as a thioredoxin-like antioxidant which may function as a tumor suppressor in some organs." (PMID 37932771, 2023). "However, tumor incidence was unchanged by host Dro1/Ccdc80 inactivation (88% in Dro1−/− vs. 83% in Dro1+/+ mice)." (PMID 35422964, 2022). "In summary, we identify Dro1/Ccdc80 as tumor suppressor in the tumor microenvironment." (PMID 35422964, 2022). "CCDC80 is a common tumor stemness marker used in a variety of solid tumor prognostic models." (PMID 35741755, 2022). "The aim of the present study was to investigate whether Dro1/Ccdc80’s tumor suppressive function is tumor-cell-autonomous." (PMID 35422964, 2022). "To investigate whether tumor suppression by Dro1/Ccdc80 is tumor-cell-autonomous, we inactivated Dro1/Ccdc80 specifically in the intestinal epithelium of ApcMin/+ mice." (PMID 35422964, 2022). "Cell-type identification by estimating relative subsets of RNA transcripts (CIBERSORT) and single-sample gene set enrichment analysis (ssGSEA) was used to explore the relationship between CCDC80 expression and the tumor microenvironment (TME) landscape of OVCA." (PMID 34820451, 2021). "We utilized cell-type identification by estimating relative subsets of RNA transcripts (CIBERSORT) algorithm and single-sample gene set enrichment analysis (ssGSEA) to explore the relationship between CCDC80 and the tumor microenvironment (TME) landscape in OVCA." (PMID 34820451, 2021). "Overall, our study demonstrated the downregulated trend of CCDC80 at both the mRNA and protein levels in OVCA, and CCDC80 may act as a tumor suppressor by affecting the TME and metabolism." (PMID 34820451, 2021).
tumor (continued). "Moreover, we found TPM4 and CCDC80, which were reported to exert a tumor repression activity, to be upregulated due to SUV39H2 knockdown." (PMID 30348215, 2018). "Furthermore, human CCDC80 can be considered a potential tumor suppressor gene." (PMID 22384085, 2012). "We demonstrate that CCDC80, localized to the nucleus, significantly reduces HGSC tumor growth and metastasis in vivo in a mouse model." (PMID 42011738, 2026). "In the tumor microenvironment, CD8+ cytotoxic T cell with high CCDC80 (another SRG) expression exhibit inhibited cytotoxicity activity." (PMID 40534859, 2025). "Therefore, we hypothesized that CCDC80 might affect the prognosis of GC by affecting tumor growth." (PMID 39308689, 2024). "The tumor microenvironment immune scoring showed a significant increase in ESTIMATE, immune, and stromal scores in the group with high CCDC80 expression." (PMID 38872096, 2024). "On the other hand, CCDC80 has been shown to reduce COAD cell proliferation by negatively regulating the ERK1/2 signaling pathway, thereby inhibiting tumor progression." (PMID 39850875, 2024). "In our data, overexpression of CCDC80 significantly suppressed CRC cell proliferation and tumor growth and induced the expression of c-MYC." (PMID 34746152, 2021). "Based on this, we speculated that CCDC80 overexpression might promote the Warburg effect and inhibit OXPHOS in tumor cells, leading to the production of more lactate, which promotes angiogenesis." (PMID 39308689, 2024). "In the present study we demonstrate that tumor suppression by Dro1/Ccdc80 is not tumor-cell-autonomous but is mediated by the tumor microenvironment." (PMID 35422964, 2022). "Because SETDB2 knockdown led to significant inhibition of cell growth, migration and invasion, we further selected six tumor- or differentiation-related genes (WWOX, CADM1/TSLC1, CCDC80, NDRG1, CA9 and FZD9) that have been reported to show altered expression in several cancers including GCs." (PMID 27572307, 2016). "Therefore, high CCDC80 expression may potentially affect the TME through M2 macrophage polarization, which could promote tumor progression 44-46." (PMID 39308689, 2024). "CCDC80 was downregulated in OVCA and may play a role as a tumor suppressor in OVCA." (PMID 34820451, 2021). "Understanding the interplay among CCDC80, LDHA and LDHB could provide insights into the metabolic reprogramming of cancer cells and identify novel targets for therapeutic intervention aimed at restoring normal metabolic processes and enhancing anti-tumor immunity." (PMID 39308689, 2024). "Additionally, CCDC80's positive correlation with LDHA and negative correlation with LDHB, although weak, implies its involvement in lactate metabolism, potentially influencing the tumor microenvironment and cancer cell metabolism." (PMID 39308689, 2024).